IGF1R (insulin like growth factor 1 receptor)
Diseases named in the same sentence as IGF1R in open-access papers (continued):
Sharing a sentence is not in itself a finding about the gene and the disease.
liver fibrosis (8 papers, 2014 to 2025). "Additionally, IGF1R deficiency has been associated with delayed liver fibrosis induced by cholestatic damage." (PMID 38059910, 2023). "Studies on liver fibrosis have revealed the core role of the IGF1/IGF1R signaling system in controlling the liver fibrosis process." (PMID 38846640, 2024). "PDGF and IGF play essential roles in the process of liver fibrosis, as EGCG can inhibit the expression of PDGFR and IGF-1R mRNAs, thereby reducing liver fibrosis." (PMID 28884125, 2017). "In carbon tetrachloride–induced rat hepatic fibrosis model, the anti-fibrotic effect of (-)-epigallocatechin-3-gallate (EGCG) has been demonstrated to be associated with its effect in down-regulation of IGF-1R expression." (PMID 24400868, 2014). "Notably, recent evidence highlights the potential of IGF1R inhibitors in mitigating liver fibrosis." (PMID 41323736, 2025). "Many studies indicate that IGF1R can promote the proliferation and transformation of HSCs into myofibroblast-like cells through activation of classical pathways, such as PI3K/AKT and MAPK/ERK, which, in turn, secrete a large amount of ECM and are closely associated with hepatic fibrosis." (PMID 41323736, 2025). "The collective results suggest that these molecules, along with their downstream effectors such as IGF1R and ZEB1, play crucial roles in liver fibrosis and may serve as promising targets for therapeutic interventions." (PMID 38511056, 2024). "Moreover, there were 192 potential targets regulated by DSLHG, of which 86 were related to liver fibrosis, including AKT1, EGFR, and IGF1R." (PMID 31354851, 2019).
mesothelioma (8 papers, 2009 to 2023). A usually malignant and aggressive neoplasm of the mesothelium which is often associated with exposure to asbestos. "Activation of IGF1R is associated with an increase in both mesothelioma cell proliferation and motility." (PMID 19603014, 2009). "Our finding that cap-mediated protein translation is associated with IGF-I stimulation suggests that IGF1R inhibition is a very attractive therapeutic target in mesothelioma." (PMID 19603014, 2009). "Importantly, the dysregulation of IGF-1 receptor (IGF-1R) signaling is implicated in the growth and tumorigenesis of many cancers, including mesothelioma." (PMID 36232554, 2022). "In support of the function of the IGF-I axis in mesothelioma development, previous data demonstrate that malignant transformation of mesothelial cells in animal models requires an intact IGF1R molecule." (PMID 19603014, 2009). "IGF1R inhibitors are currently in clinical testing and seem to have potent in vitro activity against mesothelioma cells." (PMID 19603014, 2009). "Treatment of IGF-I for 20 min stimulated the intrinsic tyrosine kinase activity of IGF1R, resulting in phosphorylation in both mesothelioma cells and control LP9 mesothelial cells." (PMID 19603014, 2009). "Increased IGF1R phosphorylation lasted for up to 300 min in two cell lines (H2461, H513), but drifted back to baseline levels in the remaining mesothelioma cells (H2373, H2052, and H2596) and control LP9 mesothelial cells." (PMID 19603014, 2009). "In the light of the findings that the effects of IGF1R activation in mesothelioma depend on the activation of the eIF4F complex, it will be interesting to combine IGF1R inhibition with agents designed to target cap-mediated translation." (PMID 19603014, 2009). "Recently, it was shown that the combination of rapamycin or PI3K/mTOR inhibitors and one specific RTK inhibitor (EGFR, MET or IGF1R inhibitor) suppressed adverse AKT activation and hampered mesothelioma cell growth in vitro and in MPM xenografts." (PMID 29755689, 2018).
pancreatic adenocarcinoma (8 papers, 2010 to 2023). "Immunohistochemical analysis of IGF-1R in pancreas adenocarcinoma tissue microarray (TMA) was done to further confirm the pathophysiological role of IGF-1R in PDAC pathogenesis." (PMID 24809702, 2014). "GIPC1 is highly expressed in human pancreatic adenocarcinoma and plays a central role the stability of IGF-1R in pancreatic adenocarcinoma cell lines." (PMID 21209904, 2010). "Since IGF-1R is known to stimulate cell proliferation, we examined the effect of silencing IGF-1R on proliferation of pancreatic adenocarcinoma cells." (PMID 24809702, 2014).
renal cell carcinoma (8 papers, 2012 to 2020). "In this work, we evaluate the anti-tumor activity of two novel IGF-1R-targeting agents against renal cell carcinoma given alone or in combination with an mTOR inhibitor." (PMID 23548153, 2013). "Up-regulation of IGF-1R has been observed in several cancers, including HCC and renal cell carcinoma." (PMID 31160483, 2019).
tongue squamous cell carcinoma (8 papers, 2012 to 2023). A squamous cell carcinoma that arises from the tongue. "MiR-7 was also reported to regulate IGF-1R expression in tongue squamous cell carcinoma cells." (PMID 23227519, 2012). "Of relevance to this study, Jiang and co-workers reported IGF1R expression, but not EGFR expression, being inhibited by miR-7 in tongue squamous cell carcinoma cells." (PMID 23115635, 2012).
cardiomyopathy (7 papers, 2009 to 2025). A disease of the heart muscle or myocardium proper. "The results suggested genes (Pdk4, Igf1r, Lipe, Serpine1, and Bcl2l1) targeted cardiovascular diseases including cardiomyopathies, ventricular dysfunction, etc.." (PMID 38961143, 2024). "In particular, Males Only DMRs selected by machine learning feature selection were able to distinguish CHD from non-CHD samples and frequently mapped to genes associated with CHDs or cardiomyopathies, including FUNDC1, ETV5, SYT9, CAMTA1, GRIA4, and IGF1R." (PMID 37803336, 2023). "We further evaluated the protein expression of 5 miR-143 targets (HK2, ERK5, IGF1R, IGFBP5 and ORP8) that have been shown to be involved in cardiomyopathy or cardiac remodeling." (PMID 32855642, 2020).
chondrosarcoma (7 papers, 2011 to 2024). A malignant cartilaginous matrix-producing mesenchymal neoplasm arising from the bone and soft tissue. "Because IGF1R signalling has been implicated in chemoresistance, four chondrosarcoma cell lines were treated with a combination of OSI-906 and doxorubicin." (PMID 27418340, 2016). "Since chondrosarcoma is resistant to chemotherapy, we explored a possible role of the IGF1R/IR pathway in chemoresistance." (PMID 27418340, 2016). "Mediators of IGF1R signalling are heterogeneously expressed and phosphorylated IRS1 was detected in 67 % of the tested chondrosarcoma cell lines, suggesting that IGF1R signalling is active in a subset of chondrosarcoma cell lines." (PMID 27418340, 2016). "Recently, functional profiling of receptor tyrosine kinases in chondrosarcomas revealed active IGF1R signalling in one out of five chondrosarcoma cell lines." (PMID 27418340, 2016). "Our study further suggests that IGF1R expression is lower in clear cell chondrosarcoma and mesenchymal chondrosarcoma compared to the other cartilage tumours." (PMID 27418340, 2016). "Ten chondrosarcoma cell lines were treated with OSI-906 (IGF1R and IR dual inhibitor) after which cell proliferation and migration were determined by a viability assay and the xCELLigence system, respectively." (PMID 27418340, 2016). "Strikingly, we detected high expression of the IGF1R in chondrosarcoma cell lines compared to primary tumours." (PMID 27418340, 2016). "This illustrates that there is limited preclinical rationale for using IGF1R inhibitors for the treatment of chondrosarcoma of bone." (PMID 27418340, 2016). "This series included 38 chondrosarcomas of which 53 % had immunohistochemical staining with an IGF1R antibody." (PMID 27418340, 2016). "Because chondrosarcoma is a very heterogenous disease, it is possible that the IGF1R directed therapy is only effective in a subset of patients." (PMID 27418340, 2016). "In addition, we found minimal IGF1R expression in primary tumours in contrast to the high expression detected in chondrosarcoma cell lines, even if both were derived from the same tumour, suggesting that in vitro culturing upregulates IGF1R expression." (PMID 27418340, 2016). "This suggests that chondrosarcoma cells upregulate IGF1R upon prolonged culturing." (PMID 27418340, 2016). "This demonstrates that IGF1R signalling is active in a subset of chondrosarcoma cell lines." (PMID 27418340, 2016). "Moreover, levels of IGF1R, that we previously showed to be artificially upregulated during culture in 2D, were negative in the spheroids, also indicating a higher similarity to chondrosarcoma in vivo." (PMID 33425984, 2020). "Furthermore, IGF1R is only minimally expressed in chondrosarcoma primary tumours." (PMID 27418340, 2016). "Heterogeneous expression of IGF1R, IR, IGF2R, IGF1, IGF2, IRS1 and IGFBP3 was seen, both at the mRNA and protein levels, in chondrosarcoma cell lines." (PMID 27418340, 2016). "Expression of mediators of IGF1R signalling and phosphorylation status of IRS1 was determined in chondrosarcoma cell lines by qRT-PCR and western blot." (PMID 27418340, 2016). "Since we previously reported IGF1R expression to be artificially upregulated in chondrosarcoma cell lines, being low to absent in chondrosarcoma primary tumor tissue but positive in 2D cultured cell lines, we assessed IGF1R in the spheroids." (PMID 33425984, 2020). "However, prolonged stable disease was achieved for chondrosarcoma patients by combining mTOR inhibitors with liposomal doxorubicin or EGFR, IGF1R, VEGF inhibitors." (PMID 33425984, 2020). "Our results indicate that the IGF pathway is not important for chondrosarcoma growth as IGF1R inhibition did not demonstrably impact chondrosarcoma cell line proliferation, migration and chemoresistance." (PMID 27418340, 2016).
chondrosarcoma (continued). "Treatment with three different IGF1R/IR inhibitors does not have an effect on chondrosarcoma cell viability, irrespective of apparent pathway activity and stimulation with IGF1." (PMID 27418340, 2016). "Although synergistic effects of IGF1R/IR inhibition with doxorubicin are described for other cancers, our results demonstrate that this was not the case for chondrosarcoma." (PMID 27418340, 2016). "In addition, IGF1R expression is low/absent in chondrosarcoma primary tumours in contrast to chondrosarcoma cell lines." (PMID 27418340, 2016). "In summary, the results of this study demonstrate that although chondrosarcoma cell lines have high IGF1R expression and activation of downstream targets, inhibition of IGF1R/IR signalling does not affect chondrosarcoma proliferation, migration and chemoresistance." (PMID 27418340, 2016). "Therefore, we conclude that there is no convincing preclinical rationale for using IGF1R/IR inhibitors in the treatment of chondrosarcoma." (PMID 27418340, 2016). "Furthermore, we did not see a difference in sensitivity to IGF1R inhibition between the mesenchymal, dedifferentiated and conventional chondrosarcoma cell lines included in this study." (PMID 27418340, 2016). "However, even after this pretreatment, chondrosarcoma cell line migration was not influenced by IGF1R/IR inhibition, illustrating that the IGF pathway does not play a role in chondrosarcoma cell migration." (PMID 27418340, 2016).
chronic lymphocytic leukemia (7 papers, 2015 to 2023). "For example, EZH2 directly binds to the IGF1R promoter along with C-Myc and upregulates IGF1R expression in a subgroup of chronic lymphocytic leukemia, resulting in activation of the downstream PI3K." (PMID 33327550, 2020). "In this study we performed an investigation of the role of IGF1R expression in a large and representative prospective series of 217 chronic lymphocytic leukaemia (CLL) patients enrolled in the multicentre O-CLL1 protocol (clinicaltrial.gov #NCT00917540)." (PMID 25786252, 2015).
clear cell renal cell carcinoma (7 papers, 2016 to 2025). "Clear cell renal cell carcinoma (ccRCC) patients with IGF1R overexpression have 70 % increased risk of death compared to patients who had tumors without IGF1R expression." (PMID 27405474, 2016). "Yuen and colleagues found that IGF1R protein levels are unaffected by hypoxia in clear cell renal carcinoma with or without VHL, but exogenously introduced VHL protein reduces both the promoter activity of IGF1R and the stability of IGF1R mRNA independent of oxygen concentration." (PMID 27460078, 2016).
colitis (7 papers, 2018 to 2025). Inflammation of the colon. "For example, covalent binding between GPX8 and caspase 4 inhibited inflammation associated with colitis, and GPX8 was involved in protection from bleomycin-induced lung injury in IGF1R knockout animals." (PMID 36750850, 2023). "In colitis-associated tumorigenesis, miR-139-5p inhibits the cross-talk between the PI3K/Akt and Wnt pathways by targetting IGF-1R." (PMID 29440459, 2018). "As it was recently shown, IGF-1R acts via LKB1/AMPK pathways at the nexus between oxidative damage, mitochondrial function, and a connection between colitis and colorectal cancer." (PMID 34769108, 2021). "IGF-1R knockout can activate the LKB1/AMPK pathway and play a protective role in colitis and CAC." (PMID 35733095, 2022). "Mechanically, heterozygous IGF-1R knock-out attenuated colitis and CAC, induced in Igf1r+/− mice." (PMID 34769108, 2021).
colorectal tumor (7 papers, 2010 to 2025). "Another study showed that serum concentration of IGF1 was higher in allele-A carrying IGF1R rs7166348 polymorphism and associated with a higher risk of colorectal neoplasm." (PMID 37284192, 2023). "In mouse models, combination treatment of OSI-906 (an IGF1R/IR inhibitor) and PF-4708671 (a p70S6K inhibitor) significantly reduces IGF1R/IR inhibitor-resistant colorectal tumor growth." (PMID 39459035, 2024). "Indeed, FURIN inhibition in human colorectal tumor cells repressed tumor metastases via inhibition of IGF1R processing in mouse models." (PMID 26137475, 2015). "It is known that EGF-R, VEGFR, IGF1R, Src, and PDK1 are overexpressed in human colorectal tumors, so the mechanism of MI-1 antitumour action could consist on inhibition of these kinases in tumor tissue." (PMID 28101521, 2016).
cutaneous melanoma (7 papers, 2013 to 2023). A primary melanoma arising from atypical melanocytes in the skin. "In humans, low IGF1R expression was associated with reduced progression-free survival in the TCGA cohort of cutaneous melanoma." (PMID 36229674, 2022). "Analysis of TCGA PanCancer Atlas (skin cutaneous melanoma) showed that patients with a BRAF mutation and high levels of IGF1R and INSR had a worse overall survival." (PMID 34831014, 2021). "However, the molecular mechanisms will require further investigation in order to completely dissect the role of the ER/IGF1R pathway in cutaneous melanoma development." (PMID 32150843, 2020).
dwarfism (7 papers, 2011 to 2025). "Evolutionary analyses reveal that structural variations in and transcriptional–translational efficiency attenuation of the IGF1R gene constitute critical mechanisms underlying dwarfism phenotypes, validated in both murine models and human genetic cases." (PMID 40430222, 2025). "Dysregulation of the IGF-1/IGF-1R axis is also associated with growth disorders such as acromegaly and dwarfism, characterized by abnormal levels of IGF-1R." (PMID 39638246, 2024). "IGF1R is located on chromosome 10 and is notoriously associated with reduced growth and dwarfism." (PMID 36980905, 2023). "Although, in our patient the profound growth deficit certainly is caused by the aberrant pericentrin genes/proteins, such findings suggest that dwarfism-like phenotypes can also be provoked by IGF1R mutations under specific, adverse genetic or environmental conditions." (PMID 22693602, 2012). "Furthermore, evidence has revealed that mice with IGF1R deficiency will suffer from dwarfism to a certain extent, and IGF1R defects can alter chondrocyte proliferation, leading to the excessive hypertrophy of growth plates in the bone extension zone and apoptosis." (PMID 35883386, 2022). "As IGF1R is closely related to the IR, partly sharing amino acid identity, increased IGF2–mediated IR signaling can rescue mouse embryonic development to prevent dwarfism in IGF1R knockout mice." (PMID 34943879, 2021). "The Igf1r+/− mouse model has allowed us to study the effect of just reduced IGF-1 signaling on lifespan/aging from the many other pathways that are affected by dietary restriction and dwarfism." (PMID 22132081, 2011).
leiomyoma (7 papers, 2010 to 2023). A well-circumscribed benign smooth muscle neoplasm characterized by the presence of spindle cells with cigar-shaped nuclei, interlacing fascicles, and a whorled pattern. "In contrast, IGF1R and related signaling pathways, classically defined as growth promoting, were not differentially expressed between the two leiomyoma groups, but were up-regulated in leiomyoma compared to myometrium as in other studies of leiomyoma." (PMID 23785396, 2013). "Most of the leiomyoma DEGs were found upregulated in F compared to the MF or M; however, some genes, including CDKN1A, L1CAM, SLC7A5, CCND1, IGF1R, and PTHLH, were only increased in MF vs. M and F vs. M comparisons." (PMID 33807176, 2021).
papillary thyroid carcinoma (7 papers, 2014 to 2022). "LncRNA PVT1 enhances the viability and invasion of papillary thyroid carcinoma cells by functioning as ceRNA of microRNA-30a to mediate the expression of insulin like growth factor 1 receptor." (PMID 32228518, 2020). "For instance, lncRNA PVT1 enhances insulin like growth factor 1 receptor (IGF1R) expression to promote cell proliferation and invasion in papillary thyroid carcinoma by acting as ceRNA of miRNA-30a." (PMID 32280300, 2020). "Compared to patients with thyroid disease, papillary thyroid carcinoma patients had the highest expression level of IGF 1 and IGF-1R protein and mRNA." (PMID 31555212, 2019).
Parkinson disease (7 papers, 2019 to 2026). A progressive degenerative disorder of the central nervous system characterized by loss of dopamine producing neurons in the substantia nigra and the presence of Lewy bodies in the substantia nigra and locus coeruleus. "Importantly, some of these same proteins were significantly associated with Parkinson's disease severity including oligomeric and phosphorylated forms of alpha-synuclein and insulin-like growth factor-1 receptor." (PMID 41783831, 2026). "Moreover, E2 reduced by 25% the synergism and increased by 36% the antagonism of IGF1R with genes involved in amyotrophic lateral sclerosis and Alzheimer's, Huntington's, Parkinson's and prion diseases." (PMID 37594177, 2023). "Furthermore, IGF‐1R/Insulin alterations are characteristic in patients with AD, Parkinson's, and other neurodegenerative disorders." (PMID 35411714, 2022). "Since E2 mediates neuroprotective effects through IGF1‐IGFR signalling, we evaluated synergistic and antagonistic interactions between IGF1R genes and genes for neurodegeneration implicated in amyotrophic lateral sclerosis and Alzheimer's, Huntington's, Parkinson's and prion diseases." (PMID 37594177, 2023). "E2 treatment led to a statistically significant antagonism of IGF1R with the subunits ATP5A1, ATP5G1, and ATP5O of the ATP synthases H+ transporting complexes and reduced the synergistic coupling with the Parkinson's disease SNCAIP (synuclein alpha interacting protein)." (PMID 37594177, 2023).